SOX7 (SRY-box transcription factor 7)
Diseases named in the same sentence as SOX7 in open-access papers (continued):
Sharing a sentence is not in itself a finding about the gene and the disease.
tumor (continued). "IHC performed on the extracted tumor body highlighted that the expression of Ki67 and PCNA was negatively linked to SOX7 expression." (PMID 39227479, 2024). "Compared to paired adjacent non-tumor tissues, the mRNA levels of SOX7 were notably decreased in 27 out of 34 LUAD tissues." (PMID 39346732, 2024). "After verification, the UMUC3 cell line with overexpression and T24 cell line with stable knockdown of SOX7 (SOX7-sh) were selected for subcutaneous tumor-bearing in BALB/c-nude mice." (PMID 39227479, 2024). "In this research, we reveal that SOX7 is diminished in BCa, suggesting its potential role as a tumor suppressor in this context." (PMID 39227479, 2024). "SOX7 is a transcription factor that regulates the cell differentiation, proliferation, migration, and apoptosis and acts as a tumor suppressor in different cancers." (PMID 37480054, 2023). "While SOX18 has been found to be overexpressed in tumours, SOX7 and SOX17 have been reported to be downregulated." (PMID 37511076, 2023). "NBAT1, another tumor suppressor lncRNA, exerts its activity through the regulation of SOX7 expression." (PMID 37047365, 2023). "When EOC cells were transfected with a miR-452-5p mimic, the SOX7 expression decreased, further affirming the oncogenic properties of miR-452-5p and its ability to regulate SOX7, which is regarded as a tumor suppressor in the existing literature." (PMID 37175530, 2023). "MeRIP-qPCR results showed that the relative level of m6A modification in HDAC9, MINDY4B was significantly increased in ALV-J induced tumor livers, while the relative level of m6A modification of SOX7 in ALV-J induced tumor livers was significantly decreased." (PMID 35529873, 2022). "As a tumor-suppressor factor, SOX7 inhibits HCC cell proliferation and induces cell cycle arrest by decreasing the expression of cyclin D1 and c-myc." (PMID 35267473, 2022). "For example, the transcription factor SRY-related HMG-box 7 (Sox7), which acts as a tumor suppressor, has been found to be downregulated in a variety of cancers including GBM and its downregulation has been associated with poor prognosis." (PMID 35223842, 2022). "SOX7 re-expression in tumor endothelial cells restored tumor growth and angiogenesis in Shp2iECKO mice." (PMID 34728626, 2021). "SOX7, SOX17, and SOX18 belong to the SOXF family and are functionally redundant; moreover, SOX7 deletion in endothelial cells reduces tumor angiogenesis and promotes tumor vascular normalization." (PMID 34728626, 2021). "SOX7 and ZsGreen immunofluorescence staining demonstrated that SOX7 was effectively and specifically induced in the tumor endothelial cells of Shp2iECKO mice." (PMID 34728626, 2021). "Together, SHP2 interacts with and stabilizes ASK1, which activates ASK1-c-Jun signaling to increase SOX7 expression in tumor endothelial cells." (PMID 34728626, 2021). "SOX7’s known properties and functions indicate its tumor-suppressor role in multiple kinds of cancers." (PMID 33152990, 2020). "For other drugs, like PTX, the silencing of miRNA-935 increases the expression of sex-determining region Y-box 7 (SOX7) and as a tumor suppressor, SOX7 can promote the antitumor effect of PTX, inducing cell growth arrest and apoptosis." (PMID 32122355, 2020). "miR-9 directly targets SOX7 (SRY-Box 7), which is a transcription factor involved in developmental processes and acting as a tumor suppressor in several cancers." (PMID 32111074, 2020). "Although the mechanisms of SOX7-mediated tumor suppression are mostly unclear in cancer cells, one study indicated that SOX7 interacted with β-catenin to promote its depletion and consequently inhibited its mediated transcription." (PMID 29757932, 2018). "Human SOX7 was demonstrated as a tumor suppressor in various malignancies, and its downregulation in cancer cells was attributed to promoter DNA methylation and microRNA-mediated inhibition." (PMID 29757932, 2018).
tumor (continued). "SOX7 is a transcription factor and acts as a tumor suppressor, but its target genes in cancers are poorly explored." (PMID 29757932, 2018). "Overall, we have identified an array of potential target genes of SOX7 and examined four of them for their roles in SOX7-mediated tumor suppression." (PMID 29757932, 2018). "Tumor formation assay was performed to further validate the AB073614/SOX7 signaling pathway in vivo." (PMID 29029454, 2017). "Sex-determining region Y-box 7 (SOX7), one of the SOX transcription factors family, has been recently recognized as a tumor suppressor implicated in human cancers." (PMID 29029454, 2017). "Here the authors show in mouse tumour xenograft models that PDGF-BB produced by tumour cells induces IL-33 via Sox7 in tumour pericytes, and IL-33 promotes metastasis through its effects on tumour-associated macrophages." (PMID 27150562, 2016). "In a recent study, we for the first time demonstrated that SOX7 behaved as a tumor suppressor through the Wnt/β-catenin signaling pathway in ovarian cancer." (PMID 27188720, 2016). "We found HCC samples exhibited lower levels of SOX7 mRNA and protein expression than non-tumor samples, and the expression of SOX7 was negatively correlated with tumor size." (PMID 24816720, 2014). "Of great interest, a recent report based on whole genomic copy number analysis demonstrates SOX7 as a novel tumor suppressor, which is silenced in the majority of non-small cell lung cancer (NSCLC) samples." (PMID 25297608, 2014). "Taken together, we found that overexpression of SOX7 suppressed tumor formation by proliferation inhibition via down-regulation of cyclin D1 and c-myc." (PMID 24816720, 2014). "Although the molecular mechanism by which SOX7 produces its tumor suppressive effects has yet to be fully determined, SOX7 has been shown to interact with β-catenin and inhibit cell proliferation mediated by the Wnt signaling pathways." (PMID 25297608, 2014). "Four weeks later, large tumors were seen in the vector groups, while the tumor volume was still minimal in those mice transplanted with the SOX7-expression cells." (PMID 24816720, 2014). "While SOX7 alterations have been seldom reported in patients with heart defects, SOX7 is a tumor suppressor in many organs." (PMID 24009689, 2013). "In PCa, SOX7 mRNA and protein expressions were both shown to be down-regulated, which was consistent with the findings of this study and was found to be due to tumor-specific promoter hypermethylation present in PCa tissues and PCa cell lines/xenografts." (PMID 22703285, 2012). "In contrast to Sox7, the upregulated β-catenin was correlated with high-grade tumor (P = 0.045), and two Wnt/β-catenin specific downstream targets; Cyclin D1 (P < 0.001) and FGF9 (P = 0.003)." (PMID 23295859, 2012). "SOX7, a tumor suppressor, is downregulated in HB tissues, whereas β-catenin is upregulated." (PMID 40136353, 2025). "These molecular alterations suggest that LARS2 and SEZ6L2 might contribute to COAD progression by promoting tumor growth and immune evasion, whereas SOX7 downregulation may facilitate tumor development by impairing tumor suppressive pathways." (PMID 40230854, 2025). "There was an inverse correlation between promoter methylation and SOX7 mRNA expression levels in diagnostic MM cases; whereas, we did not observe any relationship in tumor samples obtained at relapse." (PMID 40699642, 2025). "It will also be interesting to identify transcriptional targets of SOX7 in MM cell lines through methodologies such as ChIP-Seq and RNA-Seq to address whether SOX7 targets genes related to tumor suppression." (PMID 40699642, 2025). "Since Wnt/β-catenin signaling has been implicated in preventing CD8+ T cell recruitment, the reduced expression of SOX7 could contribute to the exclusion of cytotoxic T cells from the tumor, weakening immune-mediated tumor control." (PMID 40230854, 2025).
tumor (continued). "While LARS2 and SEZ6L2 may contribute to immune suppression and tumor immune evasion, SOX7 appears to promote CD8+ T cell infiltration and antitumor immunity." (PMID 40230854, 2025). "Restoring SOX7 expression inhibits Wnt/β-catenin signaling, reducing tumor growth and invasion." (PMID 40136353, 2025). "The tumor-suppressive effects of SOX7 may occur through the regulation of activities in different signaling pathways, primarily Wnt/β-catenin." (PMID 40699642, 2025). "If sufficient evidence for SOX7 can be obtained supporting a tumor suppressive role through functional studies, re-expression of silenced SOX7 through the administration of epi-drugs such as HDAC inhibitors can be considered as a targeted therapy option for MM and allied neoplasms." (PMID 40699642, 2025). "Targeting pathways such as the MCAM-CD163 axis or PDGF-BB/SOX7/IL-33 could reverse this immunosuppression, enhance T-cell infiltration, and disrupt tumor vascular support." (PMID 39796646, 2024). "Similarly, this investigation highlights that CYGB, as a downstream target of SOX7, plays a tumor inhibitory function with SOX7 in BCa." (PMID 39227479, 2024). "More and more evidences suggest that SOX7 has a tumor-suppressive effect." (PMID 39227479, 2024). "Down regulation of SOX7 promotes tumor cell stemness and chemo-resistance." (PMID 37480054, 2023). "Congruently, the genes upregulated in tumor-draining LN fLECs, including several transcription factors that regulate lymphatic differentiation and lymphangiogenesis (Prox1, Klf4, Sox7, and Yap1), were significantly enriched for proliferation-, migration-, and angiogenesis-related GO terms." (PMID 35892863, 2022). "However, its expression level varies greatly among different tumor types, suggesting the existence of cancer cell-dependent mechanisms to regulate SOX7 expression." (PMID 35267473, 2022). "In general, SOX7 functions as a tumor suppressor in most tumors." (PMID 35267473, 2022). "Importantly, the decrease in tumor necrosis and hypoxia in Shp2iECKO mice was significantly reversed by the expression of SOX7." (PMID 34728626, 2021). "The lack of SOX7 expression was associated with advanced tumor stages, regional lymph node metastasis, and worse prognosis in OSCC patients." (PMID 34207933, 2021). "Therefore, we proposed proangiogenic SHP2-ASK1-c-Jun-SOX7 signaling pathway responsible for regulating tumor angiogenesis and vessel abnormalization." (PMID 34728626, 2021). "The SOX7 protein has been very well described as a tumor suppressor in different types of cancer." (PMID 33152990, 2020). "SOX7 is a transcription factor and functions as a tumor suppressor." (PMID 32411609, 2020). "They further demonstrated that SOX7-repressed MTHFD2 could contribute to SOX7-mediated tumor suppression." (PMID 32411609, 2020). "SOX7 restrains tumor development by interfering with the Wnt/β-catenin signaling pathway." (PMID 31861404, 2019). "The opposite pattern of expression of Sox7 and Sox17 and the involvement of Sox18 in tumor vascularization suggests that SoxF family members may have different functions in ECs dependent on the niche, insult, or type of vascular beds." (PMID 31073164, 2019). "This phenomenon suggested that SOX7 in tumor cells may exert its regulatory role through signaling pathways distinct from these in nontumorigenic scenarios." (PMID 29757932, 2018). "SOX7 functional studies, although very limited, also suggest a tumor-suppressive role." (PMID 29757932, 2018). "Among these four genes, we determined that SOX7-activated SPRY1 and SLIT2, and SOX7-repressed TRIB3 and MTHFD2 could all differentially contribute to SOX7-mediated tumor suppression." (PMID 29757932, 2018). "However, we still lacked the knowledge regarding the genes directly regulated by SOX7 to exert its tumor suppressive activity in oncogenic processes." (PMID 29757932, 2018).
tumor (continued). "Alternatively, introducing MTHFD2 could markedly rescue cell growth caused by SOX7 overexpression, suggesting that MTHFD2 inhibition played a key role in SOX7-mediated tumor suppression." (PMID 29757932, 2018). "The role of SOX7 in promoting tumour progression and angiogenesis is poorly understood." (PMID 28577909, 2017). "Overall, the tumor inhibition effect of sh-AB073614 was abolished when SOX7 was deleted." (PMID 29029454, 2017). "However, the inhibition of SOX7 reversed the tumor-suppressive effect of silencing AB073614 in the sh-AB073614 + sh-SOX7 group." (PMID 29029454, 2017). "The expression of SOX7 was negatively correlated with tumor size." (PMID 24816720, 2014). "SOX7 has been proposed to function as a tumor suppressor in some cancers." (PMID 24816720, 2014). "Recently, SOX7 is proposed to function in tumorigenesis depending on the tumor type." (PMID 24816720, 2014). "We assessed the expression of SOX7 in ovarian tissues of different tumor progression states." (PMID 25297608, 2014). "By contrast, the protein expression level of COX2 and cyclin-D1 increased as the tumor malignancy progressed, suggesting that SOX7 may function through the Wnt/β-catenin signaling pathway as a tumor suppressor." (PMID 25297608, 2014). "Furthermore, overexpression of SOX7 suppressed tumor formation with down-regulation of cyclin D1 and c-myc in vivo." (PMID 24816720, 2014). "In summary, our study suggests that SOX7 is a tumor suppressor in the lung." (PMID 23557216, 2013). "Thus, we wanted to determine whether ectopic expression of TRIB3 or MTHFD2 could counteract the tumor suppressive activity of SOX7." (PMID 29757932, 2018). "Importantly, the genes involved in many essential cancer-related processes, such as cell death, survival, growth, proliferation and tumor morphology, showed remarkable alterations, strongly suggesting that SOX7-mediated gene transcription plays an essential role in oncogenesis." (PMID 29757932, 2018). "Thus, previous studies strongly suggested a tumor suppressive role of SOX7." (PMID 29757932, 2018). "Moreover, the frequent decline of SOX7 expression in human malignancies suggested that SOX7 might be an emerging tumor suppressor in oncogenesis." (PMID 27058905, 2016). "Our findings identify SOX7 and SOX30 as likely tumor suppressors, exhibiting reduced expression in NSCLC tissues, often through epigenetic silencing." (PMID 41373817, 2025). "In a study on colorectal cancer (CRC), SOX7 was shown in CRC cell lines and tumor tissues to be transcriptionally silenced through abnormal DNA methylation." (PMID 40699642, 2025). "To address whether deletion or methylation affects mRNA expression levels of SOX7 as well as other two tumor suppressor candidates located in del8p23.1, we first compared mRNA expression levels of SOX7 with/without del8p23.1 in patient-matched diagnostic and relapsed MM samples." (PMID 40699642, 2025). "Instead, a proangiogenic apoptosis signal-regulating kinase 1 (ASK1)/c-Jun/SRY-Box transcription factor 7 (SOX7) signaling pathway was induced by SHP-2, responsible for tumor angiogenesis and vessel abnormalization." (PMID 38999976, 2024). "It illustrated that overexpression of SFTPC inhibiting EMT process of NSCLC cells was relevant to upregulating SOX7 and repressing WNT/β-catenin pathway in tumor xenograft models." (PMID 39346732, 2024). "The ASK1-c-Jun-SOX7 signaling axis, controlled by SHP2, is also activated and contributes to tumor angiogenesis." (PMID 34728626, 2021). "Studies have revealed that miR-24 involves in tumor cell proliferation, differentiation, invasion, and metastasis by regulating numerous genes, such as PTEN, TRIM11, SOX7, PRKCH, and P16." (PMID 33550881, 2021). "In contrast, Moonlight identified SOX7, CYP26B1, DACT2 as tumor suppressors with low expression in these same cell lines." (PMID 31900418, 2020).
tumor (continued). "Our in vitro experiments demonstrated that SOX7 acts as a tumour suppressor in NSCLC cells and SOX7 overexpression suppressed TGF‐β1‐induced metastasis in NSCLC cells." (PMID 28266181, 2017). "However, the inhibition of SOX7 could reverse the tumor-suppressive effect of silencing AB073614." (PMID 29029454, 2017). "Taken together, these results strongly suggested that the tumor-suppressive effect of silencing AB073614 was, in large part, owing to its ability to activate SOX7 and subsequently inhibit the activation of Wnt/β-catenin signaling pathway." (PMID 29029454, 2017). "Our work reported here showed that SOX7 expression was correlated positively with AXIN2 and negatively with β-catenin, supporting our postulated synergy of SOX7 and AXIN2 to suppress tumor progression by promoting β-catenin degradation." (PMID 27188720, 2016). "Additionally, recent studies indicate that SOX7 may act as a tumor suppressor." (PMID 25297608, 2014). "In this study, we showed that both SOX7 mRNA and protein expression were frequently decreased in HCC tissues, and the expression of SOX7 was negatively correlated with tumor size." (PMID 24816720, 2014). "To study the role of SOX7 in HCC, we first examined the expression pattern of SOX7 in 29 paired HCC samples and adjacent non-tumor tissue samples by immunohistochemistry." (PMID 24816720, 2014). "For example, SOX7 and SOX17 have been suggested to suppress tumor growth through an interaction with β-catenin in various cancer types." (PMID 25427424, 2014). "Based on whole genome analysis to measure the expression of SOX7 on a series of non-small cell lung cancers (NSCLC), investigators have shown that SOX7 is a novel tumor suppressor gene silenced in the majority of NSCLC." (PMID 25297608, 2014). "Given that SOX7 has been identified as a tumor suppressor that regulates Wnt/β-catenin signaling, its downregulation in COAD may lead to a more immunosuppressive tumor microenvironment." (PMID 40230854, 2025). "The observation that promoter-associated SOX7 hypermethylation is also frequent in PCL cases suggests SOX7 as a mainly epigenetically silenced tumor suppressor not only in MM but also in PCL." (PMID 40699642, 2025). "Nevertheless, subsequent studies have demonstrated that the anti-tumor impact of SOX7 is not solely reliant on the regulation of Wnt signaling." (PMID 39227479, 2024). "Moreover, we discovered that SOX7 and proSP-C protein were colocalized in AT2 cells in adjacent non-tumor tissues by IHC staining." (PMID 39346732, 2024). "Knockdown of SOX7 promotes the proliferation of GBM cells, indicating that SOX7 may act as a tumor suppressor." (PMID 37047365, 2023). "By contrast, a role for SOX7 was recently described in acute myeloid leukaemia (AML), where this transcription factor was shown to block proliferation, acting in that context as a tumour suppressor." (PMID 27411892, 2016). "In summary, we identified that SOX7 could suppress tumor growth in HCC, and our investigation suggested that restoration of SOX7 would be a potential molecular target for HCC therapy." (PMID 24816720, 2014). "Compared with non-tumor samples, HCC samples exhibited lower levels of SOX7 protein expression." (PMID 24816720, 2014). "Finally, tumour mouse models lacking Sox7 expression within endothelial cells demonstrated reduced tumour growth, Treg penetration, endothelial VEGFR2 expression and aberrant vessel morphology." (PMID 36045675, 2022). "Tumor heterogeneity due to the presence of multiple genetic clones together with the presence of variable degrees of promoter hypermethylation among MM tumor samples may be responsible for the less obvious difference in SOX7 transcript expression in MM cases with/without delSOX7." (PMID 40699642, 2025). "Although the precise control of immune infiltration by LARS2, SEZ6L2, and SOX7 in CD8+ T cells and tumor fibrotic process are not yet understood, the results are promising and justify additional research." (PMID 40230854, 2025).
tumor (continued). "SOX7 expression is most prominent in the non-malignant lung tissue across both LSCC and LUAD samples, with significantly reduced levels observed within the tumor core and border." (PMID 41373817, 2025).